TBC1D26 (TBC1 domain family member 26)
Description:
May act as a GTPase-activating protein for Rab family protein(s).
Synonyms: MGC51025
Tractability: No criterion of Open Targets' tractability assessment is met for any kind of drug.
Gene: Protein-coding gene on chromosome 17 (15,732,247 to 15,746,162, forward strand). Ensembl gene ENSG00000214946.
Gene Ontology:
Molecular function: GTPase activator activity
Genetic constraint (gnomAD): Loss-of-function variants: 14 observed, 31.83 expected, observed/expected ratio (o/e) 0.44, 90% interval 0.29 to 0.69. The upper end of that interval is the gene's LOEUF score, 0.69, which puts it in group 2 of 6, group 1 being the genes least tolerant of losing a copy. Missense variants: 199 observed, 260.29 expected, observed/expected ratio (o/e) 0.76, 90% interval 0.68 to 0.86. Synonymous variants: 87 observed, 97.36 expected, observed/expected ratio (o/e) 0.89, 90% interval 0.75 to 1.07.
Homologues: Orthologues: macaque TBC1D26 (71% identical). Paralogues in human: TBC1D28 (39% identical), TBC1D3G (35% identical), TBC1D3 (35% identical), TBC1D3B (35% identical), TBC1D3C (35% identical), TBC1D3D (35% identical), TBC1D3F (35% identical), TBC1D3H (35% identical), TBC1D3I (35% identical), TBC1D3K (35% identical), TBC1D3L (35% identical), TBC1D3E (35% identical), and 33 more.
Diseases named in the same sentence as TBC1D26 in open-access papers:
TBC1D26 is named in the same sentence as 5 diseases in open-access papers, as found by Europe PMC text mining. Sharing a sentence is not in itself a finding about the gene and the disease. The quoted sentences say what the papers report.
cervical carcinoma (1 paper, 2021). A carcinoma arising from either the exocervical squamous epithelium or the endocervical glandular epithelium. "The increased sample size enabled identification of SMGs previously unreported in cervical carcinoma including NBPF10 (8%), RANBP2 (6%), MSN (6%), KRT8 (6%), POTEC (6%), ZC3H11A (4%), BMS1 (4%), GPX1 (3%), OTOP1 (3%), DNAH12 (2%), COIL (2%), TBC1D26 (2%), SPRED3 (2%), FAM115A (2%), and ARIH1 (1%)." (PMID 34620846, 2021).
lymphoma (1 paper, 2015). A malignant (clonal) proliferation of B- lymphocytes or T- lymphocytes which involves the lymph nodes, bone marrow and/or extranodal sites. "Only seven genes (7%) were significantly (as determined by MuSiC analysis) mutated in both lymphoma immunophenotype groups, such as the proteasome subunit gene PSMA1, and the genes encoding the two uncharacterized proteins FAM90A1 and TBC1D26." (PMID 26377837, 2015).
cancer (1 paper, 2015). A tumor composed of atypical neoplastic, often pleomorphic cells that invade other tissues. "In contrast, TBC1D26 is a novel cancer gene, which may allow for completely new treatments." (PMID 26377837, 2015).
TBC1D26 also shares sentences with these, for which no sentence is quoted: skin cutaneous melanoma (1 paper); T-cell lymphoma (1).